VWF (von Willebrand factor)
Diseases named in the same sentence as VWF in open-access papers (continued):
Sharing a sentence is not in itself a finding about the gene and the disease.
coronary artery disease (65 papers, 2007 to 2026). "A prior study also showed the association between high circulating vWF and adverse clinical outcomes in coronary artery disease patients." (PMID 40283058, 2025). "VWF has repeatedly been associated with coronary heart disease; however, it has been suggested that the associations are more modest than previously reported." (PMID 37255854, 2023). "Several studies have confirmed that high levels of VWF are associated with coronary heart disease and ischemic stroke." (PMID 33448867, 2021). "Recent reports have implicated that as the plasma vWF levels increase, the risk of coronary heart disease increases as well; consequently, vWF is known as an independent predictor of cardiovascular diseases." (PMID 33107067, 2021). "This unveils the thrombus-generating activity of elevated VWF-concentrations as one of the dominant causative factors for coronary heart disease." (PMID 33015097, 2020). "The association between higher plasma levels of vWF and thrombotic complications of coronary artery disease was described." (PMID 33096906, 2020). "Alongside with tissue plasminogen activator (t-PA), and D-dimer of fibrinogen, VWF is characterized as one out of three biomarkers directly associated with atherosclerotic lesions and coronary heart disease." (PMID 33015097, 2020). "In particular, increased circulating levels of tissue plasminogen activator (t-PA), D-dimer and von Willebrand factor (VWF) have been associated with increased coronary heart disease risk." (PMID 28477314, 2017). "It has been reported that higher levels of VWF are associated with a 3-fold increased risk for severe coronary heart disease." (PMID 28649180, 2017). "Association of baseline levels of t-PA antigen, D-dimer and VWF with coronary heart disease in the Reykjavik Study (1925 cases, 3616 controls)." (PMID 23408959, 2013). "We aimed to assess associations of circulating tissue plasminogen activator (t-PA) antigen, D-dimer and von Willebrand factor (VWF) with coronary heart disease risk." (PMID 23408959, 2013). "Elevated levels of vWF were observed in association with increased concentrations of particulate matter in patients with coronary heart disease." (PMID 23587270, 2013). "There is some evidence that concentrations of t-PA antigen, D-dimer, and von Willebrand factor may be more modestly associated with first-ever coronary heart disease events." (PMID 40807121, 2025). "Among other factors, elevation of von Willebrand factor levels with enhanced platelets function and increased factor X activity in the coagulation cascade have been described, all contributing to an elevated risk of coronary artery disease." (PMID 38698496, 2024). "Moreover, VWF has been proposed as an independent risk factor for VTE, and several studies have found associations between high VWF levels and arterial thrombosis, especially in subjects with coronary heart disease." (PMID 39726607, 2024). "Since VWF plays an important role in thrombocyte adhesion and formation of thrombus, it has been reported that there is a positive association of increased levels of VWF and the development of coronary artery disease and stroke." (PMID 37240845, 2023). "However, plasma vWF is a risk factor for multiple vascular diseases, including cerebral thrombosis, hypertension, and coronary disease." (PMID 31057027, 2019). "Other studies have suggested that the single nucleotide polymorphisms (SNPs) on the gene coding for VWF may lead to coronary heart diseases in advanced atherosclerotic and diabetic patients." (PMID 31620451, 2019). "This study investigated the association between plasma BNDF and vWF levels and whether these biomarkers could predict cardiovascular events at a 12-month follow-up in patients with stable coronary artery disease (CAD)." (PMID 29409455, 2018). "vWF have repeatedly been associated with increased risk of coronary heart disease." (PMID 29200971, 2017).
coronary artery disease (continued). "This might strengthen the recent suggestion that vWF is more modestly associated with coronary heart disease than previously estimated." (PMID 29200971, 2017). "One intronic SNP marker, rs216873 within the vonWillebrand factor (vWF) gene, and markers within vascular cellular adhesion molecule 1, were found to be significantly associated with depressive symptoms, especially in women with coronary artery disease." (PMID 27555379, 2017). "It is known that VWF is a risk factor for coronary heart disease." (PMID 24937073, 2014). "Due to its pivotal role in hemostatic plug formation, VWF may directly influence the likelihood of a thrombotic event, as suggested by the association of VWF levels with an increased risk of ischemic heart disease." (PMID 24453831, 2013). "This study evaluated the relationship between plasma FVIII and vWF levels and the severity of coronary artery disease (CAD), as assessed by the SYNTAX score." (PMID 41007843, 2025). "In a case‐control study and meta‐analyses of 15 studies by Willeit and colleagues, the reported adjusted odds ratio for coronary heart disease was 1.16 (95% CI 1.10–1.22) for every increase of one standard deviation from baseline of vWF levels." (PMID 36819164, 2023). "Increased vWF to collagen binding has been previously reported in pathological conditions, such as inflammation related to infection and cardiovascular diseases (coronary heart diseases and cerebral stroke)." (PMID 37505710, 2023). "A vital role in coronary artery disease is played by Von Willebrand factor (VWF), which serves as a bridge between platelets and the subendothelial matrix after vessel damage." (PMID 36684571, 2022). "Studies have shown that an elevated plasma vWF level is related to several vascular diseases, including coronary heart disease, atrial fibrillation, and hypertension." (PMID 33107067, 2021). "First, vWF is a promised indicator of the clinical outcome in patients with coronary artery disease." (PMID 32039706, 2020). "In summary, VWF A1-GPIbα binding remains pre-eminent in targeting coronary heart diseases, owing to the elevated levels of VWF specifically in these conditions." (PMID 31620451, 2019). "A meta-analysis of prospective population-based studies found relative risks for coronary heart disease per 1-SD higher baseline levels of 1.13 (95% CI 1.06–1.21) with t-PA, 1.23 (1.16–1.32) with D-dimer and 1.16 (1.10–1.22) for VWF." (PMID 28477314, 2017). "Baseline characteristics of coronary heart disease cases and matched controls in the Reykjavik Study, and correlations with t-PA antigen, D-dimer and VWF." (PMID 23408959, 2013). "Age and sex-adjusted odds ratios for coronary heart disease per 1 standard deviation higher baseline level were 1.25 (1.18, 1.33) for t-PA antigen, 1.01 (0.95, 1.07) for D-dimer and 1.11 (1.05, 1.18) for VWF." (PMID 23408959, 2013). "Considering that VWF facilitates primary hemostasis and a local inflammatory response at high shear rates, its dysfunction may contribute to the development of coronary artery disease and its complications." (PMID 39335520, 2024). "A large sample meta-analysis showed that an independent prognostic factor for MACE could be the plasma levels of VWF in patients with coronary artery disease when measured 24 and 48h after admission." (PMID 36684571, 2022). "Experimental procedure: We measured vWF multimers and the total protein carbonyl contents in the sera of 90 patients with ischemic heart disease (and 30 healthy controls) immediately before and after an RR session, three times (baseline, 6 months, 12 months), during a one-year follow-up study." (PMID 33920144, 2021). "High circulating levels of unusually large vWF multimers have strong procoagulant activity and facilitate platelet adhesion and aggregation by interacting with platelets after an acute event superimposed on coronary artery disease." (PMID 31619988, 2019).
coronary artery disease (continued). "Moreover, an early rise of vWF predicts an adverse outcome in patients with unstable coronary artery disease." (PMID 28570705, 2017). "Immunohistochemistry of coronary arteries from patients that underwent cardiac transplantation for ischemic heart disease revealed that Snail was expressed in luminal cells overlying coronary artery plaques and co-staining for von Willebrand Factor confirmed that they were of endothelial lineage." (PMID 28611395, 2017). "Recent evidence also suggests a clinical relation between VWF and coronary artery disease." (PMID 28634421, 2017). "Conversely, the elevated plasma concentrations of coagulation factor VIII and von Willebrand factor in non-O blood-group individuals has been implicated in the increased risk for thromboembolic disease and ischemic heart disease." (PMID 21799738, 2011). "Plasma concentrations of vWF are elevated in coronary artery disease and may predict future cardiovascular mortality." (PMID 19781092, 2009). "This study investigated von Willebrand factor (VWF)-mediated platelet adhesion at high shear rates in patients with premature coronary artery disease (CAD)." (PMID 37509554, 2023). "For instance, as VWF plays a prominent role in the shear-rate-dependent platelet adhesion in thrombus, agents targeting VWF interaction with the vessel wall or platelets could potentially help to prevent coronary artery disease." (PMID 37240408, 2023). "In more severe coronary artery disease and in acute decompensated heart failure with endothelial activation, there is an increase in von Willebrand factor, which could contribute to our findings that higher von Willebrand factor was found with lower LVEF in the acute phase of the ACS." (PMID 35727504, 2023). "Ristocetin-induced aggregation was inhibited by ALX-0081 in healthy individuals (at 0.4 μg/ml) and in Coronary Artery Disease (CAD) patients (at 0.8 μg/ml) with higher plasma VWF antigen levels." (PMID 31620451, 2019). "It has been shown that coronary artery disease (CAD) patients with high on-aspirin RPR have elevated levels of von Willebrand factor (vWF)." (PMID 29200971, 2017). "The male group was characterized by higher morbidity due to coronary artery disease (CAD), which resulted in higher ST2, hs-TnT and vWF levels." (PMID 34207297, 2021). "While it is well established that fibrinogen, VWF-VIII and D-dimer are associated with increased risk of coronary heart disease (CHD), there is a lack of prospective studies of coagulation markers and risk of incident HF." (PMID 28043678, 2017). "In this study, we investigated von Willebrand factor (VWF)-related parameters in 30 patients with stable coronary artery disease (CAD) and 50 patients without CAD." (PMID 39335520, 2024). "A meta-analysis characterized the prognostic value of VWF for ASCVD complications in T2DM patients by comparing plasma VWF levels in T2DM patients with and without coronary artery disease." (PMID 36187128, 2022).
hemophilia A (62 papers, 2008 to 2026). The most common form of hemophilia characterized by spontaneous or prolonged hemorrhages due to factor VIII deficiency. "Previously, it was demonstrated that the FVIII concentrate half-life is associated with pre-infusion levels of VWF in severely affected hemophilia A patients." (PMID 30873482, 2018). "The half-life and mean residence time (MRT) of infused recombinant factor VIII (FVIII) concentrate are associated with pre-infusion levels of von Willebrand factor (VWF) in severely affected hemophilia A patients." (PMID 30873482, 2018). "Our finding that F8 deficiency leads to increased plasmatic VWF levels in mice is in line with the published report that haemophilia A patients that were injected with FVIII concentrate showed reduced VWF plasma levels." (PMID 28837614, 2017). "In spite of these mechanistic insights from in vitro analyses and the wealth of studies on haemophilia A, the significance of genetic F8-deficiency, as it occurs in haemophilia A, on VWF plasma levels and immune cell infiltration of the liver is unexplored." (PMID 28837614, 2017). "For these studies, we selected 5 FVIII variants that have been established to cause mild to moderate hemophilia A due to reduced binding to VWF." (PMID 21909383, 2011). "We studied intracellular trafficking of FVIII variants implicated in mild/moderate hemophilia A together with VWF in HEK293 cells and primary endothelial cells." (PMID 21909383, 2011). "The aim of this study was therefore to analyze VWF co-storage for a panel of FVIII variants associated with mild/moderate hemophilia A due to reduced binding to VWF." (PMID 21909383, 2011). "Aside from bone marrow biopsy and FISH testing (Monosomy 13 is a worse prognosis), the conventional labs to evaluate for vWD and factor VIII deficiency (hemophilia A) are vWF antigen and activity, factor VIII activity, ristocetin cofactor test, and factor VIII binding assay." (PMID 39055971, 2024). "Differentiation of type 2N vWD (AR) from hemophilia A (XR) may also be challenging in certain situations, and if it is combined with quantitative VWF mutation, the situation can be even more problematic." (PMID 33807613, 2021). "The insight into VWF:FVIII complex formation facilitate the design of improved hemophilia A treatments, whereas the analysis of VWD mutations provides a link between genetic pathology and clinical phenotype to facilitate targeted management of patients with VWD." (PMID 31349985, 2019). "To systematically investigate the role of FVIII on VWF content in the liver endothelium, on VWF plasma levels, and VWF multimer size ex vivo, and to determine its implication in hepatic inflammation, we have used the F8-deficient haemophilia A mouse model on a pure C57BL/6J background." (PMID 28837614, 2017). "In brief, DDAVP acts to release von Willebrand factor (VWF) and factor VIII from endogenously stored reserves, thereby correcting plasma deficiencies present in mild to moderately affected patients with hemophilia A and VWD." (PMID 40723839, 2025). "In this study, we investigated the role of polyP in the VWF–FVIII complex using plasmas from patients with hemophilia A, samples in which FVIII was chemically depleted, and plasmas from patients with different types of VWD." (PMID 36430595, 2022). "In hemophilia A, the amount of circulating VWF is similar to that in healthy individuals; therefore, VWF and FVIII levels are used in the differential diagnosis of the disease." (PMID 36430595, 2022). "Individuals with normal FVIII but a mutated form of VWF that lost its affinity for FVIII present a hemophilia A-like phenotype, emphasizing the critical role of VWF in stabilizing circulating FVIII." (PMID 36361963, 2022). "On the other hand, when neither linkage analysis nor direct mutation analysis is available for any reason, several researchers have studied coagulation factor parameters such as FVIII:C/VWF:Ag ratio or FVIII:C to screen haemophilia A carriership." (PMID 35330010, 2022).
hemophilia A (continued). "In this case, factor VIII activity level of the patient was 34% and a normal level of vWF antigen, so hemophilia A was diagnosed." (PMID 34417909, 2021). "The aim of this study is to evaluate the effect of a DDAVP-induced rise in VWF concentration by intravenous administration on the pharmacokinetics of infused FVIII in hemophilia A patients." (PMID 30873482, 2018). "It has been reported that the infusion of FVIII concentrate in haemophilia A patients results in lowered VWF plasma levels." (PMID 28837614, 2017). "In line with a previous report, describing the reduction of VWF plasma levels by FVIII infusion in haemophilia A patients, we repeatedly found a 2.5-fold increase in VWF plasma levels in F8-/y mice relative to F8+/y littermate controls." (PMID 28837614, 2017). "Replacement therapy of previously untreated hemophilia A patients with plasma-derived factor VIII containing von Willebrand factor resulted in a lower incidence of inhibitors compared with patients treated with recombinant factor VIII." (PMID 27752290, 2016). "von Willebrand Factor (VWF) is an abundant plasma glycoprotein which stabilizes Factor VIII (FVIII, the protein deficient in Hemophilia A) in circulation and adheres at sites of vascular injury, where it recruits platelets." (PMID 25409031, 2014). "Conversely, when human F.VIII is infused into VWD dogs, the half-life of the infused F.VIII is markedly reduced when compared to infusing the same amount of human F.VIII into hemophilia A dogs with normal VWF levels." (PMID 22091368, 2010). "Standardized half-life studies and analysis of pre-infusion VWF and VWF-propeptide levels were performed in a cohort of 38 patients with severe haemophilia A (FVIII <1 IU/ml), aged 15–44 years." (PMID 19707594, 2009). "In type 3, there is a complete absence of detectable vWF, thus being the most severe form of vWD, which combines traits from vWD (decreased platelet function) and hemophilia A (factor VIII deficiency)." (PMID 41480429, 2025). "Clinical evidence of inhibitors in hemophilia A indicates pdFVIII products with intact VWF may be less immunogenic, resulting in a lower incidence of inhibitors than rhFVIII." (PMID 41465517, 2025). "Hence, vWD and hemophilia A can occur together if there are low levels of vWF, showing a prolonged APTT." (PMID 39055971, 2024). "(iv)a low FVIII:C/VWF:Ag is observed (ie, <0.7): the patient may have hemophilia A or 2N VWD, or the low FVIII:C reflects a preanalytical issue (eg, delayed, inappropriate transport)." (PMID 37601016, 2023). "Regrettably, this approach is problematic in the hemophilia A mouse model due to the presence of human VWF in plasma-derived FVIII/VWF and recombinant VWF products, which would indelibly affect interpretation of the immune response observed due to antigenic competition." (PMID 37720212, 2023). "Interestingly, her relative (patient 24), who we also identified as carrier of mild hemophilia A, had normal levels of vWF and FVIII." (PMID 36430862, 2022). "Considering the AUC, the FVIII:C/VWF:Ag ratio is a good screening test to detect haemophilia A carriers, as evidenced by its specificity of 96.6%; however, it may also induce false-negative results." (PMID 35330010, 2022). "No mutation was found in the proband’s F8 and VWF genes excluding her carrier status in hemophilia A or in vWD." (PMID 33807613, 2021). "Platelets could be an ideal target for gene therapy of hemophilia A as they can store neoprotein FVIII together with its carrier protein von Willebrand factor (VWF) in α-granules and act as delivery vehicles in blood circulation." (PMID 32595633, 2020). "Thus, in our platelet-targeted gene therapy protocol, the association of VWF and FVIII is pivotal for clinical efficacy in hemophilia A with inhibitors." (PMID 32595633, 2020).